APAF1 (apoptotic peptidase activating factor 1)
Diseases named in the same sentence as APAF1 in open-access papers (continued):
Sharing a sentence is not in itself a finding about the gene and the disease.
melanoma (40 papers, 2002 to 2025). A malignant, usually aggressive tumor composed of atypical, neoplastic melanocytes. "In general, apoptosis is blocked in many cancer types as in melanoma cells by the inhibition of a gene encoding the apoptotic protease activating factor-1, Apaf-1." (PMID 34445175, 2021). "E.g., melanoma inhibit the expression of a gene encoding APAF1, the apoptotic protease activating factor-1." (PMID 30682171, 2019). "In contrast, previous studies have indicated loss of Apaf-1 in melanoma cells when compared to nevi, considered to represent an indication of reduced apoptotic capacity in invasive melanoma." (PMID 19061491, 2008). "For melanoma staging, we used Breslow thickness as our criteria for evaluating Apaf-1 expression: ⩽0.75 mm, low risk; 0.76–1.5 mm, intermediate risk; 1.51–4.0 mm, high risk; >4.0 mm, very high risk." (PMID 15305193, 2004). "That inactivating mutations in the apoptosome can indeed contribute to tumour development has most impressively been demonstrated in a study that linked the loss of Apaf-1 to the development of malignant melanoma." (PMID 14647151, 2003). "Nevertheless, overexpression of Apaf-1 in melanoma cells sensitised melanoma cells to anticancer drug treatment, suggesting that loss of Apaf-1 expression may cause chemoresistance in melanoma." (PMID 15305193, 2004). "The reversion of Apaf-1 expression by the methylation inhibitor 5-aza-2′-deoxycytidine in melanoma cells suggests that hypermethylation of Apaf-1 promoter or the upstream regulators may contribute to the reduction/loss of Apaf-1 expression in melanoma." (PMID 15305193, 2004). "To assess whether reduced Apaf-1 expression is associated with melanoma progression, we examined Apaf-1 expression in 70 melanoma primaries at various stages of invasion." (PMID 15305193, 2004). "To determine if loss of Apaf-1 expression is indeed involved in melanoma progression, we employed the tissue microarray technology and examined Apaf-1 expression in 70 human primary malignant melanoma biopsies by immunohistochemistry." (PMID 15305193, 2004). "Drug-repositioning approaches with quinacrine and methylbenzethonium were shown to inhibit MITF epigenetically, restore APAF-1 activity, and resensitize resistant melanomas to MAPKi." (PMID 41465101, 2025). "APAF-1 gene dysregulation is often indicated (42%) as one of the factors inhibiting the apoptotic process in melanoma cells; namely, by directly preventing caspase-9 activation and initiation of the protease cascade." (PMID 39770908, 2024). "For example, in numerous human melanoma samples, reduced expression of Apaf-1 has been observed and correlates with disease progression." (PMID 34567159, 2021). "Cell death appeared by peptide-induced apoptosis, a process normally blocked, e.g., in melanoma by inhibition of Apaf-1." (PMID 34445175, 2021). "Previous reports have shown that APAF1 is a key regulator of apoptosis and plays an important role in chemotherapeutic resistance of melanoma." (PMID 32190895, 2020). "Lakoochin A increased the expression of the pro-apoptotic Bcl-2 family (Puma, Bax, Bad, and Bid), Apaf-1, and cytochrome c, which can be attenuated by pre-treatment with MitoTEMPOL in A375.S2 melanoma cells." (PMID 30200660, 2018).
melanoma (continued). "The role of caspases-3 and -7 in Apaf-1 proteolytic cleavages in cisplatin-induced apoptosis in melanoma cells and in macrophages following infection with E. coli have been reported before." (PMID 24734071, 2014). "For example, several melanomas restrict their Apaf-1 expression at the transcriptional level in order to block apoptosis." (PMID 19333375, 2009). "Expression of selected hypoxia markers HIF-1α (p = 0.002), CAIX (p < 0.0001), TNF-α (p = 0.008) and Apaf-1 (p = 0.002) was significantly stronger in melanomas than in benign nevi." (PMID 19061491, 2008). "Apaf-1 is involved in the mitochondrial apoptotic pathway, and studies have reported reduced expression in advanced melanoma and a possible relationship with melanoma chemoresistance." (PMID 19061491, 2008). "Expression of selected hypoxia markers (HIF-1α, CAIX, TNF-α, Apaf-1) was significantly stronger in melanomas than in benign nevi, indicating possible roles in early melanoma development." (PMID 19061491, 2008). "In our series of nodular melanomas, these markers also revealed some associations with features of aggressive tumors like increased tumor thickness and ulceration, and expression of two markers (TNF-α, Apaf-1) were further increased in melanoma metastases." (PMID 19061491, 2008). "The role of APAF-1 methylation and its inactivation have been described in malignant melanoma and human leukaemia cell lines." (PMID 17133271, 2006). "Future TMA studies of additional tumour biopsies will validate the role of Apaf-1 in melanoma progression." (PMID 15305193, 2004). "The reduction of Apaf-1 expression in melanoma biopsies observed in our study is in agreement with previous studies demonstrating inactivation of Apaf-1 in melanoma cell lines." (PMID 15305193, 2004). "Our data showed that Apaf-1 expression is significantly reduced in primary human melanomas compared to normal nevi (P=0.014)." (PMID 15305193, 2004). "In this study, to better understand the role of Apaf-1 in melanoma development, we used TMA technology and immunohistochemistry to investigate Apaf-1 expression level in primary human melanoma biopsies." (PMID 15305193, 2004). "Our data showed that Apaf-1 expression is significantly reduced in melanoma cells compared with normal nevi (χ2=6.02, P=0.014)." (PMID 15305193, 2004). "For the 70 primary melanoma cases in which Apaf-1 staining was available, there were 38 male and 32 female, with ages ranging from 21 to 93 years (mean=58)." (PMID 15305193, 2004). "Our results demonstrated that Apaf-1 expression is significantly reduced in melanoma compared to normal nevi (P=0.014)." (PMID 15305193, 2004). "Recently it was shown that cases of human melanomas have a severely diminished expression of the adapter protein Apaf-1 and are concomitantly resistant to apoptosis." (PMID 11953820, 2002). "A number of recent studies have investigated the expression of these proteins in various types of tumour cells and reported differences, for instance loss of caspase-8-expression in a number of neuroblastomas and of Apaf-1 in melanomas." (PMID 11953820, 2002). "Melanoma cells are characterized by a low sensitivity to apoptosis associated with high expression of antiapoptotic proteins of the BCL-2 family, loss of activity of Apaf-1 factor and up-regulation of the PI3K/AKT/mTOR pathway." (PMID 36674631, 2023). "our data indicate that [Apaf-1]317expression is significantly reduced in human [melanoma]D008545." (PMID 35045882, 2022). "our data indicate that Apaf-1 expression is significantly reduced in human melanoma." (PMID 35045882, 2022).
melanoma (continued). "APAF1 is a pro-apoptotic factor and known regulator of cell survival and tumor development, the depleted expression of which has been observed in malignant melanoma cell lines and specimens." (PMID 30838036, 2019). "It is reported that decreased expression of APAF1 could be interpreted as an event contributing to melanoma chemo-resistance." (PMID 27588397, 2016). "There is an inverse correlation between APAF1 expression and melanoma progression." (PMID 26116372, 2015). "Thus, there is good reason to believe that increased miR-21 expression via suppression of APAF1 prevents apoptosis in melanoma." (PMID 26116372, 2015). "APAF-1 silencing is frequently observed in melanomas and is partly due to LOH." (PMID 24709797, 2013). "Invasive growth could then arise through a genetic or epigenetic alteration suppressing apoptosis, such as loss of APAF1, PTEN, a number of which are common in VGP melanomas." (PMID 21418545, 2011). "Apaf-1 inactivation leads to chemoresistance for example in malignant melanoma cells." (PMID 16001973, 2005). "In addition, our in vitro apoptosis assay revealed that overexpression of Apaf-1 can sensitise melanoma cells to anticancer drug treatment." (PMID 15305193, 2004). "We examined Apaf-1 expression in primary melanomas and nevi by immunohistochemistry." (PMID 15305193, 2004). "Since the Apaf-1 expression is significantly reduced in melanomas and overexpression of Apaf-1 enhances anticancer drug-induced apoptosis, reversion of the reduced Apaf-1 expression should be considered in the design of novel strategies for the treatment of melanoma patients." (PMID 15305193, 2004). "Taken together, our data indicate that Apaf-1 expression is significantly reduced in human melanoma and that Apaf-1 may serve as a therapeutic target in melanoma." (PMID 15305193, 2004). "However, APAF-1 expression is significantly reduced in malignant melanomas." (PMID 37174106, 2023). "There are a few reports where caspase-activation in cancer cells may be altered, mostly by down-regulation of Apaf-1 in melanoma (although with unknown frequency) and in pancreatic cancer, and cardiomyocytes have been reported to express little Apaf-1 and to generate only low caspase-activity." (PMID 36131076, 2023). "Also, our in vitro cell survival and apoptosis assays demonstrated that overexpression of Apaf-1 in melanoma cells enhanced anticancer drug-induced apoptosis, suggesting that Apaf-1 may serve as a therapeutic target in melanoma." (PMID 15305193, 2004). "We excluded the following genes that were methylated and deleted in melanoma: PTEN, BRIMS1, FERMT3 (KIND3), AKAP12 (SSeCKS), CDKN2A, APAF-1, MTAP and MEN1." (PMID 34639015, 2021). "Furthermore, Apaf-1 inactivation is described for melanoma cells, supporting this hypothesis." (PMID 25831048, 2015). "For example, several defects in the apoptotic machinery have been reported in melanoma, such as upregulation of bcl-2, or epigenetic silencing of DAP kinase and Apaf-1." (PMID 19367282, 2009). "As chemotherapy primarily eliminates cancer cells by apoptosis, we here evaluated if the expression of key apoptosis regulators (Bax, Bak, Bcl-2, Bcl-xL, Smac, Procaspase-9, Apaf-1, Procaspase-3 and XIAP) allows prognosticating PFS in stage III/IV melanoma patients." (PMID 32054850, 2020).
melanoma (continued). "To further investigate the role of Apaf-1 in melanoma progression, we, used tissue microarray (TMA) technology and immunohistochemistry in the present study, to evaluate the Apaf-1 expression level in primary human melanoma at different stages." (PMID 15305193, 2004). "Among the 70 melanoma primaries, six cases (8.6%) showed negative, 36 cases (51.4%) weak (1+), 21 cases (30%) moderate (2+), and seven cases (10%) strong (3+) Apaf-1 staining." (PMID 15305193, 2004). "In addition, we used the melanoma cell line SK-Mel-94 which had been previously demonstrated to be resistant to anticancer drugs due to the absence of Apaf-1 expression." (PMID 38461295, 2024). "As 5-aza treatment dramatically increased APAF-1 expression in methylated melanoma or leukemia cells but not in bladder cells, the link between APAF-1 methylation and gene silencing is not clear and might be tissue-dependent." (PMID 24709797, 2013). "However, reduced Apaf-1 expression is not correlated with melanoma thickness or 5-year patient survival." (PMID 15305193, 2004). "Interestingly, TSA treatment did not result in increased Apaf1 levels in melanoma cells, suggesting that HDAC inhibitor effects on apoptotic factors may be cell-type-specific." (PMID 27342975, 2016). "However, despite the Apaf-1 reduction in melanoma, our data showed that Apaf-1 expression is not related to melanoma thickness or 5-year patient survival, suggesting that Apaf-1 reduction is an early event of melanoma tumorigenesis, possibly at the initiation stage." (PMID 15305193, 2004).
breast carcinoma (35 papers, 2010 to 2025). "SMARCA1 plays a vital role in maintaining cell survival and cell cycle progression, as inhibition of SMARCA1 leads to the upregulation of Apoptotic Protease Activating Factor 1 (APAF1) and thus increased activity of caspase 9 in primary breast cancers." (PMID 41278204, 2025). "Inhibiting RAP80 expression can upregulate the protein expression of Caspase-3, Apaf-1, cyt c, Bax and Fas; induce the apoptosis of breast cancer cells; and increase their chemosensitivity to cisplatin." (PMID 41191140, 2025). "Some proteins within cells competitively bind to Cyt c, inhibiting its interaction with Apaf-1, thereby protecting breast cancer cells from apoptosis." (PMID 41191140, 2025). "Therefore, the acceleration of Bax, attenuation of Bcl-2, Apaf-1/cytochrome c apoptosome development, and activation of caspase-9 and -3 are supposed to explain the underlying molecular mechanisms of andrographolide that induced cell apoptosis in breast cancer cells." (PMID 35684480, 2022). "The membrane potential of mitochondria in breast cancer cells was greatly reduced by DRβ-H, and Apaf-1 and Cytochrome C were released from the mitochondria to cytoplasm." (PMID 24603880, 2014). "Moreover, ECRG4 induced the formation of the Cytc/Apaf-1/caspase-9 apoptosome and promoted breast cancer cell apoptosis." (PMID 30918105, 2019). "In other cancer types, such as breast cancer, Mel has been reported to regulate several signalling pathways, including COX‐2, p300, Akt and Apaf‐1, thereby inhibiting cell proliferation and promoting apoptosis." (PMID 40804775, 2025). "Treatment of MCF-7 breast cancer cells with these compounds lowered the expression of regulators of apoptosis TP53INP1 and APAF1 (but after 48 h of incubation with o,p′-DDT, the TP53INP1 amount increased)." (PMID 35051067, 2022). "The concentration-dependent increase in the intrinsic pathway proteins like Apaf1, Caspase 9, Caspase 3, cleavage of PARP, Bax, and cytochrome c was observed in MCF7 breast cancer cells." (PMID 35615145, 2022). "Diels (ASP) induces breast cancer cells apoptosis by influencing PARP, Bax, Bcl-2, Bcl-xL, and Apaf-1 protein expression in human breast T47D and Hs578T cells through caspase-3 signaling pathways." (PMID 33807287, 2021). "Previous studies showed increased activation ability of apoptosomes in breast cancer cells and brain tumours, because of PHAPI and Apaf-1 overexpression, respectively." (PMID 24626292, 2014). "The expression of key markers associated with proliferation (MKI67, PCNA, CCNB1, MYBL2, BUB1, CCND1), apoptosis (BCL2, CASP7, CASP8, CASP9, CASP3, BAX, APAF1), differentiation (CDH1, CD24, EPCAM, ESR1, NGFR, RUNX1), and breast cancer stemness (CD44, ITGA6, DNER, ALDH1A3, ABCG2, PROCR) was assessed." (PMID 35183258, 2022).
breast carcinoma (continued). "This can be presumed that TH could be a viable option to mediate hematological parameter, and expression of Caspase-9, Apaf-1, E2, Bcl-xL and ESR1 against breast cancer." (PMID 28399853, 2017). "We have found that MCF-7 breast cancer cells transfected with LRG1 are more resistant to apoptosis induction than non-transfected cells due to cytoplasmic LRG1 binding cytochrome c and inhibition of Apaf-1 activation (Jemmerson and colleagues, manuscript in preparation)." (PMID 20831812, 2010). "TRAIL, TRAILR1, TRAF4, CASP10, and APAF1 increase upon Sin3A knockdown in MCF7, but not MDA-MB-231, breast cancer cells." (PMID 20920219, 2010).